LINC00861 (long independently transcribed non-coding RNA 861)
Gene: Long non-coding RNA gene on chromosome 8 (125,859,721 to 126,292,788, reverse strand). Ensembl gene ENSG00000245164.
Diseases named in the same sentence as LINC00861 in open-access papers:
LINC00861 is named in the same sentence as 14 diseases in open-access papers, as found by Europe PMC text mining. Sharing a sentence is not in itself a finding about the gene and the disease. The quoted sentences say what the papers report.
cervical cancer (3 papers, 2022 to 2023). A primary or metastatic malignant neoplasm involving the cervix. "Additionally, another recent study has shown that the LINC00861/miR-513b-5p axis inhibits cancer cell progression through the PTEN/AKT/mTOR signaling pathway in cervical cancer cells." (PMID 36146599, 2022). "In contrast, LINC00861 could inhibit cervical cancer's progression by competitively sponging miR‐513b‐5p." (PMID 36371574, 2022).
lung adenocarcinoma (2 papers, 2022 to 2024). A carcinoma that arises from the lung and is characterized by the presence of malignant glandular epithelial cells. "LINC00861 has been shown to be expressed in T-Cells in the tissue microenvironment (TME) of lung adenocarcinoma patients and was associated with better prognosis." (PMID 35982125, 2022). "Similarly, LINC00861 has been shown to be important in the immune response in lung adenocarcinoma, where higher levels of the non-coding RNA correlate with improved cancer prognosis." (PMID 39497054, 2024).
ovarian carcinoma (2 papers, 2022 to 2023). A malignant neoplasm originating from the surface ovarian epithelium. "Furthermore, LINC00861 is also used as a biomarker to predict survival in patients with ovarian cancer, the early diagnosis of Parkinson’s disease, and breast cancer." (PMID 36146599, 2022).
breast invasive carcinoma (1 paper, 2021). "Other studies have reported that miR-510, PVT1, CCAT1, and Linc00861 may play important roles in breast invasive carcinoma." (PMID 34220926, 2021).
COVID-19 (1 paper, 2021). A disease caused by infection with severe acute respiratory syndrome coronavirus 2. "It has been observed that increased level of LINC02207, LINC01127 was associated with the severe COVID-19 group, whereas LINC02084, LINC02446, LINC00861, LINC01871, and ANKRD44-AS1 were associated with the mild COVID-19 group." (PMID 34940755, 2021).
eczema (1 paper, 2023). "In addition, a recent blockbuster study on eczema identified TRIB1/LINC00861 as one of the crucial variants, and this change is closely related to immune cell function." (PMID 37673886, 2023).
nasopharyngeal carcinoma (1 paper, 2023). A carcinoma arising from the nasopharyngeal epithelium. "The most important LINC00861 in the model was examined in HNE1, CNE1, and CNE2 nasopharyngeal carcinoma cell lines and transfected into the cell lines CNE1 and CNE2 using the LINC00861-pcDNA3.1 construct plasmid." (PMID 37303739, 2023).
cancer (4 papers, 2021 to 2024). A tumor composed of atypical neoplastic, often pleomorphic cells that invade other tissues. "In this study, several ARlncRNAs included in the modeling process have been already reported in various malignant tumors, such as CARD8-AS1, AC060780.1, AC123595.1, UGDH-AS1, LINC00996, LINC00861, AL606489.1, HLA-DQB1-AS1, LINC00654, and LINC00847." (PMID 34956321, 2021).
infection (1 paper, 2023). The state of being infected such as from the introduction of a foreign agent such as serum, vaccine, antigenic substance or organism. "Consistent with previous studies of immune response upon infection, SNHG6 and LINC00861 were upregulated." (PMID 37391481, 2023).
LINC00861 also shares sentences with these, for which no sentence is quoted: tumor (2 papers); breast carcinoma (1); melanoma (1); Parkinson disease (1); prostate carcinoma (1).